MMP9 (matrix metallopeptidase 9)
Diseases named in the same sentence as MMP9 in open-access papers (continued):
Sharing a sentence is not in itself a finding about the gene and the disease.
lymphoma (47 papers, 2007 to 2025). A malignant (clonal) proliferation of B- lymphocytes or T- lymphocytes which involves the lymph nodes, bone marrow and/or extranodal sites. "Overexpression of Gal-7 has been associated with enhanced metastatic potential in breast and lymphoma models, driven in part by upregulation of MMP-9 and other invasion-related genes." (PMID 40710343, 2025). "These molecules are associated with a more aggressive clinical behaviour in human lymphoma, and they appear to exert their influence through two different mechanisms: MMP-9 causes ECM degradation, whereas TIMP-1 shows an anti-apoptotic action." (PMID 23641796, 2013). "Therefore, we intensively analyzed the number of tumor-associated macrophages (TAM), because they produce MMP-9 and are reportedly correlated with poor prognosis in some solid tumors and lymphoma." (PMID 24236041, 2013). "MMP9 (>−2 FC) was markedly downregulated in this type of lymphoma compared with the GCB class (left)." (PMID 41472741, 2025). "Methylation in the promoter region of the Mmp9 gene is an important mechanism for the regulation of Mmp9 in mouse lymphoma." (PMID 41150507, 2025). "Gal-7 is constitutively expressed in lymphomas and can control the spread of lymphoma cells by regulating MMP-9 expression." (PMID 40134029, 2025). "In studies on lymphoma, EGR-1, an early growth response protein 1, is expressed by stromal cells within lymphoma tissues and inhibits the transcriptional activation of the MMP-9 gene in these stromal cells." (PMID 39712025, 2024). "Patients with symptomatic lymphoma had significantly higher mean levels of MMP9 and NGAL than controls (P < 0.05 in both cases)." (PMID 37223632, 2023). "Ectopic expression of EGR1 in thymic lymphoma stromal cells downregulates matrix metalloproteinase-9 (MMP-9) expression in them and inhibits the lymphoma growth." (PMID 35923847, 2022). "MMP-2 and MMP-9, gelatinases which are capable of degrading type IV collagen, are known to be activated in lymphomas, and their activation is considered to be related to the metastasis of lymphomas." (PMID 36357882, 2022). "The serum soluble interleukin-2 receptor (sIL-2R), which is cleaved by matrix metalloproteinase (MMP) -2 and MMP-9, has been recognized as a tumor-related biomarker of malignant lymphomas." (PMID 36357882, 2022). "It was first reported in an experimental lymphoma mouse model, in which the expression of galectin-7 by lymphoma cells was shown to increase the aggressive behavior of lymphoma cells by inducing MMP-9." (PMID 34198494, 2021). "5-aza-2′-deoxycytidine, a DNA methyltransferase inhibitor, reversed hypermethylation at the MMP9 promoter (hypermethylation of a promoter represses gene transcription) and concomitantly induced MMP9 gene expression in lymphoma cell lines." (PMID 33920915, 2021). "In continuation, the same group found evidence that galectin-7 is expressed in human lymphoid malignancies and proposed that it is a critical tumor-modulating gene that controls the dissemination of lymphoma cells via MMP-9." (PMID 34827718, 2021). "Using an experimental mouse lymphoma model, where MMP-9 plays a central role, our group has recently shown that the EGF/EGR1 (epidermal growth factor/early growth response 1) pathway was involved in the repression of MMP-9 expression by stromal cells." (PMID 25897433, 2015). "The gelatinase MMP-9 and its inhibitor TIMP-1 mediate breakdown of the extracellular matrix during inflammatory and other responses, and one or both have been linked to lymphoma at the time of diagnosis." (PMID 24922518, 2014).
lymphoma (continued). "In this study, we combined the results of flow cytometry, IHC, sIL-2R levels, and MMP-9 levels to examine the mechanisms responsible for variations in sIL-2R levels in lymphoma." (PMID 24236041, 2013). "Several reports have shown that TAMs are related to poor prognosis and tumor progression in malignant tumors, including lymphoma, and we also believed that TAMs are responsible for production of sIL-2R as they were positive for MMP-9 on IHC analysis." (PMID 24236041, 2013). "This indicates the existence of other factors responsible for production of sIL-2R, and we considered MMP-9 to be the main factor responsible for production of sIL-2R through cleavage of the IL-2R α chain expressed on lymphoma cells and bystander T-cells." (PMID 24236041, 2013). "When we compared HG and LG lymphomas, MMP-9 overexpression was found in HG T-cell lymphomas respect with LG T-cell lymphomas." (PMID 23641796, 2013). "Experiments in such cells cultured with rMMP-9 and MMP-9 inhibitor confirmed MMP-9 cleavage of IL-2Rα chains on malignant lymphoma cells." (PMID 24236041, 2013). "Expression of MMP-9 in B-cells containing lymphoma cells in DLBCL and FL was detected on gelatin zymography, but not on IHC." (PMID 24236041, 2013). "Both latent and active forms of MMP-2 and MMP-9 were undetectable at gelatine zymography in lymphoma samples." (PMID 23641796, 2013). "In this regard, it is interesting to note that in some lymphoma cell lines, MMP-9 is induced by the EBV latent membrane protein-1 (LMP-1), particularly in Burkitt's lymphoma." (PMID 18954439, 2008). "Other associations were observed between risk of lymphoma subtypes and SLC23A1, SLC23A2, and MMP9 SNPs." (PMID 18636124, 2008). "Immunohistochemically, the MMP-9 gene product was localized in lymphoma cells, macrophages, and neutrophils." (PMID 18093334, 2007). "WES revealed significantly mutated genes, including several known (NCF1, MMP9, and VDR) and possibly other candidate (CNN2, MUC4, MTSS2, KMT2C, HAVCR2, and TCF19) genes, most of which were associated with the physiological activation of lymphoma cells." (PMID 41296384, 2025). "Specifically, MMP-2 and MMP-9 are central to ECM remodeling across multiple lymphoma subtypes." (PMID 41303704, 2025). "In contrast, expression of MMP-2 and MMP-9 in other lymphoma subtypes appears less pronounced than in epithelial malignancies, likely reflecting differences in stromal composition; fibroblasts dominate ECM remodeling in carcinomas, whereas lymphoid stroma is more cellularly heterogeneous." (PMID 41303704, 2025). "Similarly, in this study, vitreous MMP-2 was significantly higher and MMP-9 also tended to be high in lymphoma patients with extraocular involvement." (PMID 36357882, 2022). "In contrast, high levels of MMP-9 were favorable for the prognosis of lymphoma." (PMID 35178444, 2022). "Upregulation of MMP-2 and MMP-9 contributes to high invasion and infiltration of lymphoma cells." (PMID 35685474, 2022). "Furthermore, murine or human recombinant galectin-7 induces the expression of MMP-9 in both mouse and human lymphoma cells." (PMID 34827718, 2021). "In particular, we observed enhanced tumor angiogenesis, increasing pro-angiogenic and lymphangiogenic factors, such as VEGF, MMP-9, CCL2, and VEGFD, and a significant recruitment of tumor-associated macrophages in lymphomas of Ibtk+/-Eμ-myc compared to Ibtk+/+Eμ-myc mice." (PMID 32019112, 2020). "A previous study reported that EGF-induced EGR1 expression could be involved in the down-regulation of matrix metallopeptidase 9 (MMP9) expression in lymphoma cells." (PMID 31635309, 2019). "The inhibition of MMP9 may thus have a therapeutic benefit in lymphoma, and doxycycline may represent a means to achieve this goal." (PMID 29536017, 2018). "We hypothesize that Gal-7 modulates MMP-9 gene expression to some extent, since lymphoma cells transfected with Gal-7 antisense RNA, also showed a reduction in MMP-9." (PMID 29320431, 2018).
lymphoma (continued). "EGR-1 activation by EGF inhibited MMP9 expression and lymphoma growth." (PMID 22461839, 2012). "Therefore, the main source of MMP-9 could be macrophages and B-cells containing lymphoma cells are also the producer of MMP-9 in tumors." (PMID 24236041, 2013). "First, we investigated whether IL-2Rα chains on lymphoma cells are cleaved by MMP-9." (PMID 24236041, 2013). "Cluster 1 (top right) included genes such as CD79A, PTPRC, EZH2, MMP9, IKBKB, or CASP8, which were upregulated in GCB lymphomas (top right colored in orange)." (PMID 41472741, 2025). "MMP-9 treated unpurified CH2-aIgM ADC, revealed 8-9-fold increased half maximal effective doses compared to the parental unmasked ADC in target lymphoma cells." (PMID 37841262, 2023). "Boxplots visualizing levels of GDF15, endostatin, MMP9, and NGAL in ng per mL, in controls and in patients with asymptomatic and symptomatic lymphoma." (PMID 37223632, 2023). "HMGB-1 in turn promotes the secretion of IL-8 and MMP-9 by keratinocytes, which result in epidermal inflammation and the invasiveness of ALK+ lymphoma cells, respectively." (PMID 28895885, 2017). "The mRNA expression of MMP-9 and MMP-2 was studied as an inducer of angiogenesis in the tumor microenvironment of metastatic liver of lymphoma bearing mice." (PMID 24932681, 2014). "However, tumor-associated macrophages (TAMs), but not lymphoma cells, were positive for MMP-9." (PMID 24236041, 2013). "Previously published data have shown bi-directional signaling during contact between tumor cells and target tissue, in particular lymphoma cells and the endothelial cells can result in high expression of MMP-2 and MMP-9 in both cell types." (PMID 19662219, 2007). "The current study examined the prognostic value of MMP1 in DLBC lymphomas to check if it reflects invasive behavior, yet MMP9 expressed no significant value." (PMID 35083113, 2022). "Importantly, the treatment of a lymphoma cell line with a DNA methylation inhibitor resulted in reduced methylation of the MMP-9 promoter, resulting in increased expression of MMP-9." (PMID 30730976, 2019). "Since MMPs, especially MMP2 and MMP9 play important role in tumor invasion and in metastatic process, and are activated in TME in DLBCL, we next evaluated the stimulatory effect of lymphoma TEXs on MMP2 and MMP9." (PMID 30103789, 2018). "A possible limit in the study is the lack of lymphoma tissue; so far, further experiments should be directed to identify the catalytic activity of MMP-9 and MMP-2 in B-cell and T-cell lymphomas." (PMID 23641796, 2013). "Therefore, increased expression of MMP9 and ROR2 may play important roles in the survival of lymphoma cells following treatment with TCP plus doxorubicin." (PMID 38514636, 2024). "A direct relationship between increased MMP-9 activity and immune competence and/or protection from lymphoma has not been described, leading us to speculate that the relationship between MMP-9 and A-NHL may be a protective one which warrants further exploration." (PMID 24922518, 2014).
metabolic syndrome (46 papers, 2008 to 2025). A cluster of metabolic risk factors for CARDIOVASCULAR DISEASES and TYPE 2 DIABETES MELLITUS. "European patients with metabolic syndrome and the MMP-9 -1572T allele are more susceptible to cardiovascular events." (PMID 36835040, 2023). "Elevated levels of matrix metalloproteinase (MMP)-9 have been associated with the metabolic syndrome (MetS) and cardiovascular events." (PMID 25191702, 2014). "Another interesting finding that possibly contributes to our hypothesis that MMP-9 is linked to systemic inflammation was lower MMP-9 levels among patients with inactive TED formally diagnosed with dyslipidemia and on HMG-CoA reductase inhibitors." (PMID 39259164, 2024). "Interestingly, similar to what we have found in our case, patients with metabolic syndrome also display increased circulating concentrations of pro-MMP-9, MMP-8, and TIMP-1, which were associated with increased concentrations of pro-inflammatory mediators and adhesion molecules." (PMID 20161799, 2010). "The MMPs, particularly MMP-2 and MMP-9, are elevated in patients with morbid obesity, metabolic syndrome, and T2DM." (PMID 39766340, 2024). "In another study, MMP9 and its inhibitors’ concentrations correlated with BMI, waist circumference, and metabolic parameters in patients with metabolic syndrome." (PMID 37445827, 2023). "In the context of metabolic syndrome, serum concentration of MMP9 has been found to be positively correlated to age, systolic blood pressure, waist circumference and fasting blood glucose levels but negatively correlated to HDL cholesterol." (PMID 37445827, 2023). "MMP-1 seems to be involved in the development of adipose tissue, while plasma levels of MMP-2 and MMP-9 are elevated in patients with the metabolic syndrome." (PMID 34512552, 2021). "Studies in humans have shown that the plasma levels of MMP-2 and MMP-9 are elevated in patients with the metabolic syndrome." (PMID 34512552, 2021). "Lox-1/PKC-α/MMP9 was upregulated by dyslipidemia, and those signal pathways increased TGF-β and SMAD2/3, which induced EndMT." (PMID 33574986, 2021). "Studies suggest that specific MMPs, such as MMP-2 and MMP-9, play a fundamental role in cardiac remodeling and degradation of the extracellular matrix in individuals with dyslipidemia." (PMID 32881885, 2020). "MMP-9 seems to be particularly related to cardiovascular disease (CVD) risk factors and metabolic syndrome (MetS)." (PMID 31890043, 2019). "In metabolic syndrome patients, SFA consumption (38 E%) was associated with upregulation of pro-inflammatory genes (MMP-9 and TNF-α) and downregulation of anti-inflammatory genes (IκBα) in a postprandial state, compared with MUFA (43 E%), in PBMCs." (PMID 28076613, 2017). "MMP-9 serum levels increased or decreased following an exercise program in healthy men and men with metabolic syndrome, respectively." (PMID 26903712, 2016). "In patients without a metabolic syndrome, neither the T-allele occurrence nor MMP-9 activity were associated with the risk of an event." (PMID 36835040, 2023). "Plasma concentrations of MMP-2 and MMP-9 are increased in patients with metabolic syndrome." (PMID 35769087, 2022). "Since the concentrations of MMP-2 and MMP-9 are higher in patients with the metabolic syndrome and TIMP-1 is significantly higher in obese patients, we assumed that the higher concentrations of the analyzed markers are the consequence rather than the cause of cardiometabolic complications." (PMID 30245717, 2018). "MMP-9/TIMP ratios are specifically influenced by weight, with the suggestion that the ratios may be biomarkers for obesity-related diseases such as cardiovascular disease and metabolic syndrome, which are conditions associated with PCOS." (PMID 39796177, 2025). "MMP-9 concentrations were lower among patients with inactive TED, formally diagnosed with dyslipidemia and on HMG-CoA (3-hydroxy-3-methyl glutaryl-CoA) reductase inhibitors (523.47 ± 303.58 vs. 1,860.44 ± 1,442.38; P = 0.0250)." (PMID 39259164, 2024).
metabolic syndrome (continued). "In the group of patients with dyslipidemia and the confirmed presence of unstable atherosclerotic plaque, plasma levels of OPG, OPN, MMP-2, and MMP-9 are significantly higher compared to the group of healthy people." (PMID 35743980, 2022). "MMP-9 was significantly elevated and positively correlated with BTM, inflammation and dyslipidemia markers." (PMID 34610044, 2021). "Intriguingly, in subclinical inflammatory conditions where MMP-9 is elevated, such as CAD, COPD and metabolic syndrome, white blood cell count (WBC) is frequently elevated, although MMP-9 and WBC are usually studied separately." (PMID 23825535, 2013). "Conversely, MMP9 levels were not different between patients with and without dyslipidemia (P = 0.29)." (PMID 36609276, 2023). "Additionally, MMP-9 levels and MMP-9/TIMP-1 ratio were negatively correlated with endothelium-dependent response in obese and metabolic syndrome people." (PMID 34625635, 2021). "The plasma levels of MMP-2 and MMP-9 are elevated in patients with metabolic syndrome, with or without diabetes mellitus." (PMID 30245717, 2018). "The aim of this study is to investigate the plasma levels of MMP-1, MMP-2, MMP-3, MMP-9, TIMP-1, TIMP-2 and their ratios in a large variety of study groups including overweight people and obese people with or without metabolic syndrome and non-obese healthy people with total of 479 participants." (PMID 34625635, 2021).